MELK (maternal embryonic leucine zipper kinase)
Diseases named in the same sentence as MELK in open-access papers (continued):
Sharing a sentence is not in itself a finding about the gene and the disease.
tumor (continued). "These pharmacological data indicate that upregulation of MELK contributes to the survival of tumor cells, particularly when they suffer from radiation insult." (PMID 25852826, 2015). "Tumor weights were less in the NCI-N87/MELK-shRNA group compared with the NCI-N87/nc-shRNA group (0.21 ± 0.13 g vs. 1.63 ± 0.39 g, P < 0.01)." (PMID 24885567, 2014). "In contrast, MELK overexpression promoted tumor growth (1.6 ± 0.50 g vs. 0.54 ± 0.14 g, P < 0.01) and peritoneal spreading and metastasis (22.3 ± 7.06 vs. 14.9 ± 3.38, P < 0.01)." (PMID 24885567, 2014). "Ninety-eight pairs of tumor and non-tumor gastric tissues were stained, and the MELK protein was found to be localized in the cytoplasm." (PMID 24885567, 2014). "Elevated MELK expression is featured in multiple tumors and correlated with tumorigenesis and tumor development." (PMID 24885567, 2014). "Many studies have shown that MELK is highly expressed in tumors and this expression is correlated with tumor grade and prognosis." (PMID 24885567, 2014). "We examined here MELK expression in clinical tissue samples and cell lines, and found that MELK mRNA and protein expression were both elevated in tumor tissues." (PMID 24885567, 2014). "Previously, we found that MELK knockdown prevents GSCs from proper mitotic progression, resulting in accumulation of tumor cells in the G2/M phase, generation of polyploid cells with multiple micronuclei, and subsequent apoptotic cell death." (PMID 24739874, 2014). "Here we demonstrate that MELK expression is elevated in tumor-derived primary human gastric tissues compared to normal controls at both mRNA and protein levels." (PMID 24885567, 2014). "Using this database, coexpression of MELK in GBM tumor samples was confirmed (p < .0001) with FOXM1 expression." (PMID 23404835, 2013). "Considering the results of preclinical studies, MELK is described as a potential anticancer target in diverse tumor entities." (PMID 24185907, 2013). "MELK knockdown decreases the transformed phenotype of multiple tumor cell lines as determined by in vivo xenograft assays as well as in vitro proliferation and anchorage-independent growth." (PMID 24185907, 2013). "The exact function of the MELK gene product (MELK) in normal and tumor biology remains to be determined." (PMID 23785665, 2013). "A xenograft tumor model of HCC-LM3 with RFA treatment was constructed to determine whether MELK expression regulates sensitivity to RFA treatment." (PMID 39871325, 2025). "Moreover, MELK levels increased significantly with tumor progression, showing higher expression in advanced-stage compared to early-stage ccRCC." (PMID 40709174, 2025). "It showed that RFA treatment upregulated the expression of MELK in tumor tissues." (PMID 39871325, 2025). "MELK knockdown in Hepa1-6 cells significantly attenuated tumor growth in mouse xenograft models." (PMID 38970074, 2024). "In addition, we confirmed that tumor cell-intrinsic MELK inhibition is beneficial in stimulating M1 macrophage polarization, hindering M2 macrophage polarization and inducing CD8 + T-cell recruitment, which are dependent on the alteration of CCL2 expression." (PMID 38970074, 2024). "MELK regulates the G2/M transition of the cell cycle and promotes tumor proliferation and survival." (PMID 39596419, 2024). "Notably, our findings provide a novel interaction atlas of tumor cells and the TME in MELK-deficient HCC." (PMID 38970074, 2024). "Silencing MELK or EZH2 or overexpressing LATS2 suppressed tumour formation in nude mice." (PMID 38652219, 2024). "Furthermore, MELK CRISPR knockout (KO) suppressed lung metastasis, and treatment with MELK-In-17 suppressed tumor growth in mouse models." (PMID 37377604, 2023). "Studies have shown that MELK could promote the progression of tumor cells by activating the PI3K/mTOR signaling pathway, catalyzing the PDHc, and reprogramming the morphology and function of mitochondria." (PMID 37949877, 2023).
tumor (continued). "In addition, in vivo, we observed that overexpression of both miR-21-5p and MELK resulted in tumor enlargement, rapid growth, and increased weight in nude mice, which was significantly alleviated by the addition of erastin." (PMID 37008632, 2023). "Maternal embryonic leucine zipper kinase(MELK) promotes tumorigenesis and tumor progression through the PI3K/mTOR pathway, which exerts its effects partly by targeting the pyruvate dehydrogenase complex(PDHc) and reprogramming the morphology and function of mitochondria." (PMID 37949877, 2023). "In the current study, we also showed that MELK-In-17 suppressed the CSC phenotype and reversed EMT in vitro and inhibited tumor growth in mouse models, further supported by the impaired tumor growth in mice bearing xenografts of MDA-MB-231 cells in which MELK was knocked out." (PMID 37377604, 2023). "CEACAM1, CEP55 and MELK were involved in tumor, inflammation, necrosis, and proliferation." (PMID 37589542, 2023). "MELK may also play a vital role in the microenvironment of HCC by regulating various tumor-infiltrating immune cells." (PMID 35693941, 2022). "Further investigation indicated that miR-101-3p has tumor-suppressing functions upstream of MELK." (PMID 35511171, 2022). "Altogether, it suggested that MELK may participate in immune response in the tumor microenvironment through affecting immune cells." (PMID 35693941, 2022). "Moreover, in the TCGA cohort, overexpression of MELK was associated with shorter disease-free survival (DFS) (3.6 years vs. 8.6 years, p < 0.001), more advanced tumor stage and overall stage, lymph node metastasis, and death during follow-up." (PMID 36151566, 2022). "The high expression levels of MELK are correlated with tumor progression and poor prognosis." (PMID 36353126, 2022). "Moreover, the ESTIMATE score, immune score, stromal score, and 29 kinds of immune cells were obviously higher in the high-MELK expression subtype than in the low-MELK expression subtype, while tumor purity showed the opposite expression trend." (PMID 36353126, 2022). "Inhibition of MELK sharply lessened tumour growth and decreased tumour volume." (PMID 33962400, 2021). "Furthermore, the tumor-suppressive activity owing to BBOX1-AS1 knockdown was partly reversed by MELK overexpression." (PMID 33931086, 2021). "Furthermore, RNA interference and inhibitor studies have shown that inhibiting MELK activity in cultured mammalian cells suppresses tumor cell growth." (PMID 34550356, 2021). "Furthermore, in human TNBC, genetical or pharmacological inhibition of MELK induces radiation sensitivity in vitro and significantly delays xenograft tumor growth in combination with radiation therapy in multiple models." (PMID 32047721, 2020). "In HCC, high MELK protein expression was not only related with short disease-free survival and overall survival but also correlated with vascular invasion and higher pathological tumor-nodule-metastasis stage." (PMID 32047721, 2020). "Consistently, we also confirmed that enforced expression of MELK in ESCC cells by transfection with MELK-overexpressing plasmid significantly promoted the tumor cell proliferation, colony formation, anchorage-independent growth in vitro, and also enhanced the tumor growth in nude mice models." (PMID 32047721, 2020). "Further, MELK expression increased in concert with tumour progression." (PMID 31821699, 2020). "Similarly, the size and weight of tumors were also obviously inhibited by MELK shRNA, suggesting that silencing MELK suppressed the tumor growth of ESCC cell in nude mice." (PMID 32047721, 2020). "MELK also plays an important role in tumor resistance and DNA repair." (PMID 33520717, 2020). "The tumor burden decreased dramatically following MELK knockdown, and even treatment with IL-1 couldn't rescue the growth (p < 0.01)." (PMID 31380279, 2019). "MELK involved in the process of cell cycle, cell proliferation, tumor formation and apoptosis." (PMID 31844590, 2019).
tumor (continued). "MELK may also play a key role in tumor resistance to therapies and DNA repair, as MELK inhibition significantly increases the sensitivity to radiotherapy and chemotherapy in various models." (PMID 31861475, 2019). "Cytoplasmic, but not nuclear, expression of MELK was associated with increased Gleason score and higher tumour stage." (PMID 29437778, 2018). "Consistent with this hypothesis, we discovered that MELK transcript expression closely mirrors tumor mitotic activity." (PMID 29417930, 2018). "MELK may function in an overlapping or redundant pathway with other mitotic kinases, several of which are up-regulated along with MELK in tumor cells." (PMID 28337968, 2017). "Among these, OTSSP167 is the most potent, with subnanomolar activity against MELK and broad-spectrum efficacy in in vitro and in vivo tumor models of various tissue origins; these encouraging preclinical results spurred initiation of a clinical trial of this compound for patients with solid tumors." (PMID 28926338, 2017). "MELK was expressed in 71.9% (128/178) of the GC tumor tissue samples." (PMID 26701722, 2016). "In contrast, MELK knockdown has little effect on luminal tumor cells, such as MCF7." (PMID 24844244, 2014). "Recent studies have shown that MELK plays an important role in tumorigenesis and tumor development." (PMID 24885567, 2014). "In this study, we report that MELK, a novel oncogenic kinase that emerged from an unbiased, in vivo tumorigenesis screen, may indeed be a therapeutic target in this tumor type." (PMID 24844244, 2014). "We previously demonstrated that MELK is abundantly expressed in GBM with preferential expression in GSCs and that targeting MELK-mediated pathways disrupt cell cycle progression of GSCs in vitro and tumor growth in vivo, suggesting that MELK is a clinically relevant molecular target for GBM therapy." (PMID 24739874, 2014). "However, the effect of MELK knockdown on tumor growth and metastasis was more profound than MELK overexpression." (PMID 24885567, 2014). "Likewise, wild-type MELK cooperates with a second oncogene, for example NeuT, to induce tumor formation in vivo." (PMID 24844244, 2014). "Due to tumor heterogeneity, whether all patients respond well to MELK knockdowns remains a concern." (PMID 39871325, 2025). "Moreover, the antitumor role of miR-505-3p was also further validated in vivo experiments, in which miR-505-3p mimic treatment substantially suppressed the growth and progression of tumor, and the MELK expression was significantly downregulated in response to miR-505-3p mimic treatment." (PMID 38970074, 2024). "Accordingly, we found that low MELK and ALK mRNA expression is associated with a significantly improved patient RFS rate, depending on whether the patient carries a tumor with the ERα-positive/PR-positive/HER2-negative or the ERα-positive/PR-negative/HER2-positive phenotype, respectively." (PMID 38589728, 2024). "Moreover, the tumour‐promoting potential of MELK has been reported in LUAD." (PMID 38652219, 2024). "IHC staining confirmed MELK KO and showed a reduction in the expression of Ki67, vimentin, and fibronectin in tumors from mice inoculated with MELK KO cells, suggesting that MELK KO reduces proliferation of tumor cells and inhibits EMT in vivo and thereby suppresses lung metastasis." (PMID 37377604, 2023). "Moreover, MELK upregulation was significantly correlated with positive tumor size and advanced TNM/histological stage, suggesting that MELK may promote HCC progression." (PMID 37949877, 2023). "Thus, the superabundantly expressed miR-21-5p facilitates tumor progression through MELK in HCC." (PMID 37008632, 2023). "However, the function of MELK in the tumor microenvironment, which plays a vital role in regulating tumor progression, is still largely unknown." (PMID 36353126, 2022).
tumor (continued). "Maternal embryonic leucine zipper kinase (MELK) is a member of the AMPK/Snf1 family, and its encoded serine/threonine kinase is involved in various physiological and pathological processes, such as cell cycle regulation, cell proliferation, apoptosis, embryonic development, and tumor development." (PMID 35440604, 2022). "This suggested that MELK may have a potential promoting role in tumor development." (PMID 35693941, 2022). "Furthermore, silencing of MELK suppressed tumour growth in vivo, and experimental research verified that MELK may augment OSCC development via mediating the Wnt/Notch signalling pathway." (PMID 33962400, 2021). "Furthermore, immunoblotting assay also showed that the protein levels of MELK, phospho-FOXM1 (T600), and its downstream targets (PLK1, Cyclin B1 and Aurora B) were much higher in tumor cell lysates derived from MELK-overexpressing mice than those from the control group." (PMID 32047721, 2020). "Moreover, the knockdown of MELK expression in H1299 also reduced the tumor growth in nude mice." (PMID 33262323, 2020). "Thus, it is possible that MELK represents a surrogate marker of E2F1 activation in this tumor type and might be helpful to select people to be treated with CDK4/6 inhibitors." (PMID 31861475, 2019). "Also, we envisaged the possibility that MELK is a prognostic marker for this tumor type." (PMID 31861475, 2019). "Thus, a small molecule inhibitor of MELK that particularly suppresses MELK activity may suffer an undesired off-target effect in both normal and tumor cells." (PMID 31412643, 2019). "Moreover, the obvious reduction of P65 expressing profiles was detected in the MELK insufficient tumor confirming that NF-κB activity could be affected by MELK." (PMID 31380279, 2019). "To better understand both MELK‐dependent and MELK‐independent effects of OTS167 that might contribute to its anti‐tumour effects in vitro and in vivo, we performed an antibody array interrogating 674 phosphorylation sites on 400 proteins, using lysates from OTS167‐treated C4‐2b cells." (PMID 29437778, 2018). "This underscores the possibility that MELK upregulation may be involved in tumor formation." (PMID 25852826, 2015). "MELK may also play an interesting role in tumor resistance to therapies." (PMID 25852826, 2015). "Moreover, a significant association of MELK expression with disease status also exists within the subtype of BBC, suggesting that MELK expression is associated with tumor aggressiveness and poor prognosis in this disease." (PMID 24844244, 2014). "By interacting directly with NSCLC cell Smad family members (Smad2, Smad3, and Smad4), MELK inhibits EMT and increases tumor cell motility, invasion, and metastasis." (PMID 40925573, 2025). "Based on existing studies, both MELK and EIF4A1 are highly expressed in tumor cells, and high EIF4A1 expression has been confirmed to correlate with poor patient prognosis." (PMID 40709174, 2025). "More importantly, phosphorylation of the transcription factor signal transducer and activator of transcription 3 (p-STAT3) is a biomarker of tumor growth and metastasis, which was decreased after RFA treatment after MELK deprivation and RFA treatment." (PMID 39871325, 2025). "MELK or RFA treatment inhibited the progression of liver tumors, and combined group enhanced this anti-tumor effect." (PMID 39871325, 2025). "MELK promotes tumorigenesis and progression via activation of PI3K/Akt/mTOR signaling, stabilization of EZH2, histone methylation, and regulation of the tumor immune microenvironment." (PMID 41278210, 2025). "The expression of MELK and SHCBP1 was then evaluated in the GSE118897 and TCGA-STAD datasets, and the findings demonstrated that both genes were markedly overexpressed in tumor tissues." (PMID 40657397, 2025). "Tumor size, volume, and weight were significantly lower in RFA-treated and MELK knockdown groups than those in sham group and were lowest in group combining MELK knockdown with RFA treatment." (PMID 39871325, 2025).
tumor (continued). "Subsequent univariate Cox and LASSO regression analyses narrowed the selection to five key genes—GGT6, HAO2, SLPI, MELK, and EIF4A1—whose expression patterns correlated strongly with tumor grade, clinical stage, and metastatic status." (PMID 40709174, 2025). "MELK-mediated macrophage polarization also indirectly affected the recruitment and activity of CD8+ T cells, further inhibiting tumor growth." (PMID 39871325, 2025). "According to immunoblotting, lowered MELK and EZH2 expression and elevated LATS2 expression were observed in tumour tissues of nude mice injected with H1975 cells transduced with sh‐MELK." (PMID 38652219, 2024). "Both downregulation of MELK and EZH2 contributed to enhancing the weight and volume of subcutaneous tumours in nude mice." (PMID 38652219, 2024). "MELK expression remained unchanged, EZH2 expression decreased and LATS2 expression was augmented in tumour tissues of nude mice injected with H1975 cells transduced with sh‐EZH2." (PMID 38652219, 2024). "In our microarray analysis, we identified potential downstream targets of MELK, including STAT5 and NFKB target genes, as well as genes involved in tumor progression and metastasis (i.e., EMT, angiogenesis, hypoxia, and apical junction)." (PMID 37377604, 2023). "For this reason, the biological consequences of the interaction between MELK and BCL-G remain to be determined as it has been demonstrated that MELK expression correlated with tumor mitotic activity in one of the studies using MELK knockout." (PMID 37031274, 2023). "The protein levels of MELK and PYCR1 were upregulated in tumor tissues compared with adjacent tissues." (PMID 37340189, 2023). "First, we analyzed the expression levels of MELK, PYCR1, and PML according to the TCGA database, and we showed that the three hub genes were upregulated in ccRCC tumor tissues compared with matched normal tissues." (PMID 37340189, 2023). "We also examined MELK regulation in HCC by noncoding RNAs (ncRNAs), as well as an investigation of its function in terms of methylation, tumor infiltration, biomarker expression, and immune checkpoint analysis." (PMID 35511171, 2022). "A subtype-specific level of MELK expression was observed in the AA-enriched samples, with the highest expression in BLBC subtype compared to other tumor subtypes (p < 0.001)." (PMID 35749404, 2022). "Based on the gene expression data retrieved from the TCGA database, 4 of the 20 DEmRNAs (CAP2, CDKN3, MELK and UBE2T) were upregulated in tumor tissues, and the remaining DEmRNAs were upregulated in adjacent normal tissues." (PMID 33879119, 2021). "The tumor markers CDKN2A and KRT7 were the most upregulated genes with fold changes 10.7 and 4.8, respectively, while markers for proliferation (MELK, CDK1, MKI67, CCNB2, BUB1, FOXM1, CDKN3) had fold changes spanning from 2.0–2.7." (PMID 35008799, 2021). "High expression of MELK was observed in ESCC cell line and human samples, especially in the metastatic tumor tissues." (PMID 32047721, 2020). "Previous studies have found OTS514 has anticancer effects in TOPK expressing tumours by regulating FOXM1 and MELK expression." (PMID 32960500, 2020). "There was a clear trend of increasing gene expression levels of MET, MELK, SDC1 and TOP2A in primary tumor compared to normal samples." (PMID 31412643, 2019). "Moreover, rescue experiments determined that both the protein expression and tumor proliferative activity owing to MELK silencing could be partly reversed by LINC02418 overexpression, indicating that LINC02418 promoted CRC cell proliferation dependent on stimulating MELK expression." (PMID 31358735, 2019). "Specifically, MELK induces EZH2 phosphorylation, which subsequently binds to and methylates NF-κB, leading to tumor proliferation and persistence of stemness." (PMID 31380279, 2019). "When baited with MELK, immunoprecipitated STRAP were significantly reduced both in sanguinarine and cisplatin treated tumor tissues extracts." (PMID 29783958, 2018).